PDGFRA (platelet derived growth factor receptor alpha)
Diseases named in the same sentence as PDGFRA in open-access papers (continued):
Sharing a sentence is not in itself a finding about the gene and the disease.
astrocytomas (continued). "In astrocytoma and other nervous system tumors, MN1 gene rearrangements (such as MN1-BEND2 and MN1-CXXC5) drive tumor occurrence via activating the PDGFRα signaling pathway." (PMID 41019085, 2025). "Consistent with parent recurrent tumor cells, amplifications of CDK4 and MDM2 and PDGFRA gain were found, while CDKN2A/B was identified as homozygous deletion in the xenografts, qualifying for integrated diagnosis of astrocytoma, IDH2-mutant, CNS WHO grade 4." (PMID 38012788, 2023). "Consistent with YMG25R parent tumor cells, gain of PDGFRA and amplification of CDK4 and MDM2 were observed, while CDKN2A HD was identified in the xenografts, qualifying for astrocytoma, IDH-mutant, CNS WHO grade 4 according to the WHO CNS5 criteria." (PMID 38012788, 2023). "To verify if IDH1/2-mutant astrocytomas with CDKN2A, PDGFRA, CDK4, or MDM2 CNA promotes poor prognosis, we used the GLASS and MSK diffuse glioma datasets (total 1,448 cases)." (PMID 38012788, 2023). "In IDH1-mutant astrocytoma cases with available clinical and CNA data (total 161 cases), we found that tumors harboring either CDKN2A deletion, PDGFRA amplification, CDK4 amplification, or MDM2 amplification conferred poor prognosis in these cohorts." (PMID 38012788, 2023). "In non-TCGA IDH1/2-mutant astrocytomas, CCND2 alteration (HR: 3.05), EGFR amplification (HR: 2.43), CDKN2A/B loss (homozygous or heterozygous loss, HR: 2.28), 22q loss (HR: 1.97), and PDGFRA alteration (HR: 1.92) were negatively prognostic." (PMID 39164213, 2025). "Similarly, in the context of the IDH mutant astrocytoma, the tumor with higher AUP1 was significantly correlated with PI3K-AKT-MTOR pathway (EGFR, PDGFRA, TSC2, MTOR), and autophagy signaling (ATG4B)." (PMID 37029364, 2023). "Furthermore, CDKN2A was completely inactivated in all the grade 4 IDHmut astrocytomas with PDGFRA amplification in TCGA and GLASS data with an exception of two cases (one in the GLASS and one in TCGA dataset), which carried only a PDGFRA amplification." (PMID 37932833, 2023). "It has been demonstrated that PDGFRA amplification is correlated with IDH1 mutation and associated with poorer prognosis in IDH1-mutant astrocytomas, CNS WHO grade 4, as compared to those without PDGFRA amplification." (PMID 38012788, 2023). "We also identified several mutations not previously reported in pediatric astrocytoma, some of which (EGFR, PIK3CA, PDGFRA) represent potentially actionable targets." (PMID 19924296, 2009). "These clinical and preclinical findings support the role of PDGFRA gene alterations and downstream multiple signaling pathways, including PI3K/AKT/mTOR pathway and RAS/RAF/MEK/ERK pathway, in promoting progression of not only IDH1-mutant, but also IDH2-mutant astrocytoma." (PMID 38012788, 2023).
HCMV infection (26 papers, 2012 to 2026). "HCMV infects multiple cell types including stem cells; referring to the fact that Thy-1 and platelet-derived growth factor receptor alpha (PDGFRα) stem cell markers enhance HCMV infection, stem cells are susceptible to HCMV infection." (PMID 34566995, 2021). "The seven alanine exchange mutations were introduced into PDGFRα-Fc and the purified soluble receptor mutants were tested regarding their ability to inhibit HCMV infection." (PMID 33780515, 2021). "The aim of this study was to analyze the potential of PDGFRα derivatives previously found to inhibit cell-free HCMV infection with respect to inhibition of cell-associated spread." (PMID 34578361, 2021). "We determined if HCMV infection altered PDGFRA expression because the PDGFRα is associated with increased metastasis." (PMID 34575976, 2021). "For the effector cells, we used human retinal pigment epithelial (ARPE-19) cells, which are susceptible to HCMV infection but have low endogenous expression of platelet-derived growth factor receptor alpha (PDGFRα), which ensures low background fusion in the absence of target cells." (PMID 40981481, 2025). "Both PDGFRA gene and protein expression were detected in mesenchymal cells during the first and second trimesters, suggesting that these cells are susceptible to hCMV infection." (PMID 40163451, 2025). "Thus, fibroblasts expressed similar levels of PDGFRα and Nrp2, which made fibroblasts more susceptible to HCMV infection compared to epithelial cells." (PMID 31336680, 2019). "The stem cells are permissive to HCMV with Thy-1 and platelet-derived growth factor receptor alpha (PDGFRα) identified as stem cell markers that favor HCMV infection." (PMID 38893091, 2024). "Several molecules, such as EGFR, Integrin αvβ3, CD90, CD147, Neuropilin-2, and platelet-derived growth factor receptor alpha (PDGFRα), have been identified as receptors or co-receptors for HCMV infection in fibroblasts, epithelial, or endothelial cells." (PMID 37146061, 2023). "First, among the multiple cell types infected by HCMV, the stem cells are permissive to HCMV, and stem cells markers such as Thy-1 and platelet-derived growth factor receptor alpha (PDGFRα) favor HCMV infection." (PMID 35458542, 2022). "First, among multiple cell types infected by HCMV, the stem cells are permissive to HCMV and stem cells markers such as Thy-1 and platelet-derived growth factor receptor alpha (PDGFRα) favor HCMV infection." (PMID 36366560, 2022). "We identified 971 positively selected genes in P. larvata, and one known human viral receptor gene PDGFRA is positively selected in P. larvata, which is required for human cytomegalovirus infection." (PMID 35583674, 2022). "The present study focused on PDGFRα, which is important for HCMV infection of fibroblasts, epithelial and endothelial cells." (PMID 34575976, 2021). "Conversely, HCMV infection decreased PDGFRA expression, potentially attenuating signaling through this receptor." (PMID 34575976, 2021). "This is compatible with the downregulation of PDGFRα by HCMV infection of coronary artery smooth muscle cells and fibroblasts." (PMID 34575976, 2021). "Both peptides, GT40 and IK40, are located in the extracellular domain of PDGFRα and were recently described to inhibit cell-free HCMV infection." (PMID 34091753, 2021). "We and others have demonstrated previously that a soluble PDGFRα-Fc fusion protein efficiently inhibits cell-free HCMV infection." (PMID 33780515, 2021). "We have previously reported that PDGFRα-Fc inhibits both trimer and pentamer-dependent HCMV infection with similarly high efficiency." (PMID 33780515, 2021). "Like the complete extracellular domain of PDGFRα, certain peptide derivatives thereof can also inhibit HCMV infection, albeit at much higher molar concentrations." (PMID 34201364, 2021).
HCMV infection (continued). "Using these vectors, we found that overexpression of EGFR and PDGFRα in hiPSCs, which are resistant to HCMV infection, rendered these cells permissive to TB40/E infection, supporting the idea that both EGFR and PDGFRα are important mediators of HCMV infection." (PMID 33205055, 2020). "A PDGFRα–neutralizing monoclonal antibody (MAb) antibody, Gleevec (an inhibitor of PDGFRα kinase activity), and PDGFRα-specific siRNAs blocked HCMV infection of fibroblasts." (PMID 23028311, 2012). "Notably, PDGFRα-positive fibroblastic cells also support productive virus replication during primary murine cytomegalovirus infection." (PMID 37248241, 2023). "PDGFRα-Fc has been shown to be a promising inhibitor of HCMV infection." (PMID 33780515, 2021). "While the decoy receptor PDGFRα-Fc and its peptide derivatives have been shown to inhibit cell-free HCMV infection, it is unclear whether they can also impede the cell-associated growth of the virus." (PMID 34578361, 2021). "Whereas murine cytomegalovirus gene transcription in PDGFRα-positive fibroblastic cells is almost completely silenced at 5 months post-infection, these cells give rise to reactivated virus ex vivo, arguing that they support latent murine cytomegalovirus infection." (PMID 37248241, 2023). "However, using this decoy receptor against HCMV infection could also affect cellular signaling due to its ability to bind the natural ligands of PDGFRα." (PMID 33780515, 2021). "However, using PDGFRα-Fc as a decoy receptor against HCMV infection could potentially impair cellular signaling by sequestration of the natural ligands of PDGFRα." (PMID 33780515, 2021). "Following binding of the HCMV trimer gH/gL/gO to its cellular receptor PDGFRα, gH/gL/gO activates the fusogenic activity of gB, thus inducing fusion of the viral envelope with the cell membrane using a pH-independent pathway, finally resulting in productive HCMV infection of fibroblasts." (PMID 31336680, 2019). "The PDGFRα-Fc mutants were tested regarding affinity to PDGF, interference with cellular signaling and inhibition of HCMV infection." (PMID 33780515, 2021). "We show that soluble derivatives of the platelet-derived growth factor receptor alpha (PDGFR-alpha), a putative receptor of HCMV, can inhibit HCMV infection of various cell types." (PMID 28403220, 2017). "Two recent studies had shown that soluble gHgLgO and also gO peptides bind to cell surfaces of PDGFRα-positive and -negative cells and interfere with HCMV infection." (PMID 40705828, 2025). "Even the least potent of the combination mutants, PDGFRα-Fc I139E + Y206S + V242K, fully blocked HCMV infection at 2000 ng/ml, while no binding to PDGF was observed even at the highest concentration tested (720,000 ng/ml = 4.35×10−6 nmol/l)." (PMID 33780515, 2021). "The mutations were quantitatively tested in biological assays for interference with PDGF-dependent signaling as well as inhibition of HCMV infection and biochemically for reduced affinity to PDGF-BB, facilitating quantification of PDGFRα-Fc selectivity for HCMV inhibition." (PMID 33780515, 2021). "Consistent with a previous study reporting that PDGFRα activation is required for HCMV infection, it was discovered that the virus phosphorylated PDGFRα in fibroblasts, but not in epithelial cells, which lack PDGFRα." (PMID 31336680, 2019). "We concluded that expression of PDGFRα can dramatically increase HCMV infection of human and non-human cells." (PMID 23028311, 2012). "Ectopic expression of guinea pig cell receptors restored GPCMV infection but not human NRP2/PDGFRA, indicating a basis for the species-specific barrier for GPCMV and HCMV infection." (PMID 41805587, 2026). "HCMV infection of HEL299 fibroblasts resulted in a pro-inflammatory environment, whereas infection of PDGFRα-positive Hs578T cells did not." (PMID 34575976, 2021).
non-small cell lung carcinoma (25 papers, 2012 to 2026). A group of at least three distinct histological types of lung cancer, including non-small cell squamous cell carcinoma, adenocarcinoma, and large cell carcinoma. "A recent report identified that copy-number variations (CNVs) of PDGFRA might be implicated in the resistance of ALK-positive non-small cell lung cancer to targeted therapies." (PMID 32005261, 2020). "Other mutations observed in isolated cases included EGFR G721A, which has been shown to respond to Gefinitib or Erlotinib in non-small cell lung cancer and PDGFRA H845Y which has been shown to respond to Imatinib." (PMID 29100278, 2017). "Although many molecular genetic studies indicate that there are some genetic mutations in non-small cell lung cancer (NSCLC), including EGFR, KRAS, PIK3CA, BRAF, ALK, DDR2, and PDGFRA, only a few studies have focused on the genetic events of salivary gland-type lung carcinomas." (PMID 26575266, 2015). "Immunoprecipitation followed by phosphoproteomics using mass spectrometry demonstrated that RTKs including ALK, ROS fusion proteins, PDGFRα, and DDR were found to be highly phosphorylated in non-small cell lung carcinoma cell lines and tumor samples." (PMID 35711942, 2022). "In non-small cell lung cancer (NSCLC) models in particular, ganetespib effectively destabilizes a number of oncogenic drivers, including the KRAS effector CRAF and PDGFRα, that in turn inactivates downstream MAPK and AKT signaling to induce apoptosis." (PMID 23530663, 2013). "In conclusion, the genetic mutations associated with PACC are different from those implicated in non-small cell lung cancer, and EGFR, KRAS, BRAF, ALK, PIK3CA, PDGFRA, and DDR2 may not be driver genes in PACC; we must identify other genes for targeted therapy against PACC." (PMID 26373952, 2015).
Obesity (25 papers, 2018 to 2026). Accumulation of substantial excess body fat. "Taken together, these data indicate that, under obesogenic conditions, the loss of EPAC1 specifically in PDGFRα+ cells reduces the thermogenic capacity of brown/beige fat and exacerbates obesity." (PMID 38195707, 2024). "Interestingly, ASPC3 was uniquely enriched for COL1A1, COL6A1, FN1, LOX, and LUM, which are fibrosis markers recently associated with a specific subset of PDGFRA+ progenitor cells in murine model of obesity." (PMID 36313560, 2022). "In summary, loss of BBS8 leads to obesity due to adipocyte hypertrophy and WAT remodeling, which is driven by primary cilia dysfunction in Pdgfrα-expressing cells." (PMID 40836034, 2025). "Taken together, we have identified an important regulatory role for Pdgfrα in islet β-cell growth and/or survival, glucose metabolism, obesity and insulin resistance." (PMID 41234234, 2025). "The platelet-derived growth factor receptor alpha (PDGFRα) gene in ADSCs is a major regulator of AMT transformation in obesity." (PMID 38686209, 2024). "We pinpoint the effects of EPAC1 to PDGFRα-positive preadipocytes, and the loss of EPAC1 in these cells impedes BAT growth and worsens diet-induced obesity." (PMID 38195707, 2024). "As PDGFRα can also be activated by PDGF-AA in WAT, these findings suggest caution on specificity of adipocyte progenitor subset activation is required when designing therapeutics manipulating PDGFRα signaling to treat obesity and diabetes." (PMID 35557517, 2022). "During HFD-induced obesity, PDGFRα+CD9hi progenitors express ECM to promote AT fibrosis, whereas PDGFRα+CD9lo progenitors are prone to undergo adipogenesis." (PMID 36229481, 2022). "PDGF-BB/PDGFRβ signalling is associated with obesity and metabolic dysfunction, and PDGFRα activation was shown to switch APC plasticity towards a profibrotic phenotype, and led to obesity-induced WAT fibrosis." (PMID 34714716, 2021). "HFD feeding triggers the recruitment of PDGFRα+ cells and obesity induces CD9 expression in PDGFRα+ cells, which become fibrotic cells." (PMID 32553115, 2020). "We found that Pdgfrα-Cre mediated knockout of Ahr protected mice from HFD induced obesity and liver steatosis." (PMID 32730300, 2020). "Meanwhile, harnessing adipogenesis by facilitating activation of the PDGFRα-Nrf2 anti-adipogenic signaling pathway is an interesting avenue to oppose excessive WAT expansion leading to obesity." (PMID 32059739, 2020). "Given that knockout of AHR (whole body or Pdgfrα-Cre mediated) can protect against obesity, it is reasonable to propose that this metabolite is an AHR agonist." (PMID 32730300, 2020). "Others have detected elevated α-SMA expression levels in a subset of SVF cells (PDGFRα+, CD9high) with obesity in C3H male mice." (PMID 29799877, 2018). "SWIF(r) also identified SNPs within three other genes (PDGFRA, SIDT2, and PHACTR3) that have previously been associated with obesity and metabolism phenotypes." (PMID 29459739, 2018). "Pdgfra plays a role in age-dependent β-cell proliferation and expansion, but how Pdgfrα affects islet β-cell function and glucose metabolism in obesity and type 2 diabetes was previously unknown." (PMID 41234234, 2025). "Similarly, Pdgfrα-Cre Ahr-floxed (Ahrfl/fl) knockout mice demonstrated protection from HFD-induced obesity and maintained small adipocyte size." (PMID 37443781, 2023). "Notably, higher levels of PDGFRα-positive high CD9-expressing adipocyte progenitors were identified in patients with obesity and glucose intolerance or diabetes." (PMID 35557517, 2022). "Collectively, our results show that knockout of Ahr mediated by Pdgfrα-Cre is protective against diet-induced obesity and suggest a mechanism by which enhanced UCP1 activity within BAT might confer these effects." (PMID 32730300, 2020). "For instance, PDGFRα‐positive adipocyte progenitor cells become CD9‐high and acquire profibrotic properties during the development of obesity." (PMID 40667744, 2025).
Obesity (continued). "A more specific study showed that a subset of PDGFRα+ cells with high CD9 expression, induced by obesity, originates pro-fibrotic cells, while those with low CD9 expression are committed to adipogenesis." (PMID 32553115, 2020). "Therefore, targeting PDGFRα activation and signaling in APCs may be an interesting avenue to oppose increased adipocyte hyperplasia underlying excessive WAT expansion leading to obesity." (PMID 30848691, 2019). "Investigating the pathophysiological roles of PDGFRA+ DPP4- nonadipogenic niche cells (AFECs) in obesity-induced insulin resistance and metabolic dysfunction would be worthwhile." (PMID 39465352, 2024). "We demonstrate that Pdgfrα-Cre Ahr-floxed (Ahrfl/fl) knockout mice are protected from HFD-induced obesity compared to non-knockout Ahrfl/fl mice (control mice)." (PMID 32730300, 2020). "Although we observed that obesity has significant effects on the mRNAs characteristic of ICC and smooth muscle cells it did not affect expression of the three mRNAs we examined that would be characteristic of PDGFRα -positive fibroblasts." (PMID 31221130, 2019). "PDGFRA was found to decrease in women with PCOS, but after stratifying for BMI, it no longer differed between groups, indicating that it was a feature of obesity rather than PCOS per se." (PMID 40072105, 2025). "Here, we used platelet-derived growth factor receptor alpha (Pdgfrα)-Cre mice, a Cre model previously established to knock out genes in preadipocyte lineages and other cell types, but not liver cells, to further define AHR’s role in obesity." (PMID 32730300, 2020). "Interestingly, in the current study, we found that knock out of Ahr using Pdgfrα-Cre, a model that has been shown in lineage tracing studies to act in preadipocytes, but not the liver, protected mice from HFD-induced obesity and steatosis." (PMID 32730300, 2020).